ALB (albumin)
Diseases named in the same sentence as ALB in open-access papers (continued):
Sharing a sentence is not in itself a finding about the gene and the disease.
Cirrhosis (continued). "We found that FFP utilization was higher in patients with encephalopathy, cirrhosis, longer duration of surgery, elevated AST, increased PT, and lower serum albumin level." (PMID 30487957, 2018). "Patients with decompensated cirrhosis showed significantly elevated levels of ALT, AST, and TBIL level in contrary to a reduced ALB level." (PMID 30508917, 2018). "In comparison with the control group, the decompensated cirrhosis group showed significantly elevated levels of ALT, AST, and TBIL, but a reduced ALB level (all P < .05)." (PMID 30508917, 2018). "We found albumin, creatinine, cholesterol, LDL, TG, HDL, hemoglobin, sodium and magnesium to reduce significantly with increasing cirrhosis severity." (PMID 29643898, 2018). "The combination of the PLT count (< 15.3 × 104/μL), albumin concentration (< 4.0 g/dL), and AAR (> 0.9; i.e., the PLALA score) is a good predictor of cirrhosis in patients with NAFLD based on data from the Japan Study Group of NAFLD (JSG-NAFLD) group." (PMID 29177681, 2018). "Independent predictors of HCC among all cirrhosis etiologies included: age, male sex, Hispanic ethnicity, high serum alpha fetoprotein, alkaline phosphatase and AST/√ALT ratio and low serum albumin and platelet count." (PMID 30260995, 2018). "Along with that, we didn’t observe any significant differences between groups regarding serum albumin, serum bilirubin, serum AFP, tumour numbers, tumour size, tumour stage, cirrhosis, HBsAg, HCV, ICG clearances." (PMID 29212179, 2017). "The mean of total Bilirubin was 3.87 ± 4.14 mg/ml, albumin was 3.89 ± 0.75 g/L, the rate of SMA and cirrhosis at entry were 56.7% and 30.6 respectively." (PMID 28977835, 2017). "At last, age, gender, α-fetoprotein (AFP), γ-glutamyl transferase (GGT), hyaluronic acid (HA), Albumin and platelet (PLT) were included in the nomogram for cirrhosis." (PMID 29235488, 2017). "As expected, the clinical variables including ALT, AST, bilirubin, INR, albumin, AFP, and platelet count significantly differ between the fibrosis and cirrhosis groups." (PMID 27688741, 2016). "During the liver functional compensation period in patients of cirrhosis, IMAT/albumin also has a short compensation period and then declined progressively with the deterioration of liver function." (PMID 28101103, 2016). "Real-life data have strongly suggested that an increased number of bacterial infections occurs in patients with cirrhosis receiving triple antiviral therapy with TVR or BOC, especially those with low platelets and low albumin levels." (PMID 27861593, 2016). "Liver became more dysfunctional during cirrhosis; instead, TBS/albumin values of these patients increased." (PMID 28101103, 2016). "As disease progressed to cirrhosis, compensatory increases of TBS/albumin were seen to overcome the adverse effect of decreased albumin levels." (PMID 28101103, 2016). "This study of albumin infusion for patients with decompensated cirrhosis and ARF or SBP demonstrated that albumin has a dose-dependent effect on survival in both patients with ARF and SBP." (PMID 26178624, 2015). "Patients without prior primary care access at diagnosis were more likely to be lost to follow-up, and had significantly worse markers of liver disease such as cirrhosis on biopsy, platelets, INR, albumin, bilirubin, and ascites." (PMID 26215250, 2015). "Next, we compared gene expression profiles in young and old patient groups after adjusting for significant confounding factor such as Edmondson grade, etiology, cirrhosis, AJCC T stage, albumin level and AFP level." (PMID 26093092, 2015). "In univariate analysis, platelet count, albumin level, Child-Pugh score, APRI, the FIB-4 index, and the LFI were significant factors for the diagnosis of cirrhosis." (PMID 25180031, 2014).
Cirrhosis (continued). "First, although the severity of cirrhosis was commonly based by Child-Pugh score or Mayo Clinic model for end-stage liver disease score, it was not possible to identify the laboratory data such as bilirubin, albumin, prothrombin time, or creatinine by ICD-9 coding numbers in this database." (PMID 25255022, 2014). "RFA is safe and effective for managing HCC with cirrhosis, especially for patients with HCC ≤3 cm and higher baseline albumin levels." (PMID 23922893, 2013). "HP α and α-2 isoforms, CLU, retinol binding protein, TTR, albumin, AGP and hemoglobin delta were decreased in the cirrhosis stage but IgJ chain was increased." (PMID 24066001, 2013). "Among the biochemical markers assessed, we showed that albumin, globulin, GGT, CHE, TBA, PT, INR, CP and PLT were predictors of cirrhosis." (PMID 24282481, 2013). "We derived a new fibrosis-cirrhosis index (FCI) comprised of ALP, bilirubin, serum albumin and platelet count." (PMID 21507271, 2011). "The decreased serum albumin, the increased bilirubin and ASAT by BDL cirrhosis all confirm impaired liver function." (PMID 16968543, 2006). "Among patients with cirrhosis, 38 had CTP class A, 14 had CTP class B, and one had CTP class C. Patients with CTP class B tended to be older and had lower preoperative hemoglobin and albumin levels than those in class A." (PMID 41590349, 2026). "The following 16 parameters showed a statistical difference between AIH patients with and without cirrhosis: age, ALB, GLO, ALT, AST, ALP, WBC, Hb, PLT, IgG, C3, C4, ANA titer, and comorbidities such as depression, extrahepatic AIDs, and enlarged ALN." (PMID 41503678, 2026). "LPC species did not correlate with AST, ALT, or albumin levels, indicating that plasma levels are not closely related to liver function in patients without cirrhosis." (PMID 41007672, 2025). "A study revealed that albumin played an important role in the prevention and management of patients with cirrhosis through its oncotic and non-oncotic properties." (PMID 41001124, 2025). "The results showed that JQC treatment was effective in alleviating the progression of cirrhosis in a dose-dependent manner, as evidenced by the restoration of serum markers (ALT, AST, TBIL, HA, ALB) and the amelioration of liver histopathology, including reduced necroinflammation and fibrosis." (PMID 41383461, 2025). "In hierarchical clustering, compensated and decompensated cirrhosis could be moderately well distinguished, primarily based on ZFP, albumin and sodium levels." (PMID 40317887, 2025). "The emerging model, named PLAN-B, comprised ten baseline parameters: cirrhosis, age, platelet count, entecavir/tenofovir, sex, serum ALT and HBV-DNA, albumin and bilirubin levels, and HBeAg status, and it showed significant superiority over the previous models in both validation cohorts." (PMID 39941182, 2025). "Although ALB levels increased at liver transplantation compared to exploration, a negative growth in ALB was indicative of more severe cirrhosis progression." (PMID 41210866, 2025). "Applying further exclusion criteria yielded our final cohort of 736 patients with ascites secondary to cirrhosis who underwent 2 LVPs within 30 days, of whom 301 received albumin and 435 did not receive albumin." (PMID 41021268, 2025). "Albumin, a plasma-derived protein with both oncotic and non-oncotic properties, has long been employed in cirrhosis management." (PMID 41140983, 2025). "This highlights that albumin should not be viewed as a universal solution but rather as an essential component of tailored management strategies for cirrhosis." (PMID 41140983, 2025). "The protective effect of albumin in cirrhosis can be explained by both its oncotic and non-oncotic properties." (PMID 41140983, 2025). "Likewise, laboratory parameters including platelet count, WBC count, and ascitic fluid levels of albumin, were important predictors of SBP in cirrhosis patients." (PMID 38797850, 2024).
Cirrhosis (continued). "Our study demonstrates that higher albumin at admission and non-MASLD cirrhosis etiology were associated with higher odds of AKIN resolution, whereas higher Cr at admission was associated with lower odds of AKIN resolution." (PMID 39518516, 2024). "Multivariate logistic regression analysis identified the following six factors as risk factors for 30-day mortality: performance status (PS) ≥ 2, albumin level < 3.0 g/dL, blood urea nitrogen (BUN) ≥ 25 mg/dL, C-reactive protein (CRP) ≥ 1.0 mg/dL, comorbid metastatic cancer, and cirrhosis." (PMID 38438534, 2024). "For example, the presence of ascites alone is recognised as a sign of decompensated cirrhosis, while a decline in serum albumin is not an independent indicator of decompensation that affects the prognosis in a similar weight." (PMID 39421189, 2024). "For instance, sodium, bilirubin, and albumin levels, which are typically used in traditional scoring systems such as the Child–Pugh score or MELD-Na score for cirrhosis, reflect cirrhotic status and correlate with mortality and morbidity in patients with cirrhosis." (PMID 39272704, 2024). "Assessment showed no obvious radiological signs of cirrhosis, bilirubin 13 μmol/L, albumin 26 g/L, and prothrombin time international normalized ratio (PT–INR) of 1.1, corresponding to Child–Pugh B in the presence of cirrhosis." (PMID 39313807, 2024). "This study aimed to assess the impact of albumin therapy on prognosis in ICU patients with cirrhosis and non-HRS AKI." (PMID 39434907, 2024). "Currently, the benefit of albumin infusion in cirrhosis patients with non-HRS AKI remains controversial." (PMID 39434907, 2024). "In another study, albumin infusions failed to consistently improve circulatory function in patients with cirrhosis and ascites." (PMID 38551716, 2024). "In contrast, albumin did not demonstrate a significant beneficial effect on overall survival in long-term infusion for ascites recurrence in patients with cirrhosis." (PMID 38139434, 2023). "Serum albumin level is a component of CPS and is a crucial parameter in patients with cirrhosis." (PMID 36983211, 2023). "Moreover, although patients were matched by gender, age, region of origin, HBeAg status and bilirubin, patients with HBV monoinfection had less progressive disease indicated by albumin, INR, and platelet count and had less frequent cirrhosis." (PMID 37789170, 2023). "Albumin infusion does not exhibit uniform effectiveness across all forms or complications of cirrhosis." (PMID 38139434, 2023). "A meta-analysis including a total of 1297 cirrhotic patients showed that BCAA supplementation can significantly increase muscle mass, serum albumin and BMI, and reduce cirrhosis-related complications, but offered no significant benefits in terms of mortality." (PMID 36765884, 2023). "The parenclitic network mapping can predict the survival of patients with cirrhosis and identify patient subgroups that do not benefit from targeted albumin therapy." (PMID 37019645, 2023). "Unadjusted hazard ratio [HR] of the intermediate albumin group, compared with the high albumin group, were 3.6 for death or OLT, 11.2 for liver-related death, 4.6 for HCC, 8.2 for decompensated cirrhosis, and 6.2 for gastroesophageal varices (all risks were statistically significant)." (PMID 37432160, 2023). "Whereas, in an open-label multicenter trial ATTIRE, increasing albumin infusion in patients with decompensated cirrhosis showed no more benefit due to most of the patients suffering alcohol-related liver disease." (PMID 37539053, 2023). "Intriguingly, serum IGF-1 levels were the only significant prognostic factor in patients with compensated cirrhosis, whereas serum albumin (but not IGF-1) levels in those with decompensated cirrhosis." (PMID 37554499, 2023). "It should be noted that administration of albumin in patients with bacterial infections other than SBP has not been shown to prevent SBP or improve survival in patients with cirrhosis." (PMID 38202206, 2023).
Cirrhosis (continued). "Interestingly, we found that PBC patients with NAFLD had lower levels of serum ALB<LLN, PLT<LLN, and cirrhosis, but higher rates of hypercholesterolemia and survival." (PMID 38027142, 2023). "Two patients with CP-B cirrhosis were reported with a temporary shift to CP-A (n = 1 each per 1 mg BID and placebo), and 1 patient reported a temporary shift to CP-C (1 mg BID) due to decreased serum albumin." (PMID 37889522, 2023). "Previous studies have shown the beneficial effects of albumin administration on overall survival and bacterial infection rates in patients with cirrhosis;181,174 however, its effects on neutrophil function have not been investigated within clinical studies." (PMID 37822786, 2023). "Among patients with biopsy-proven NAFLD, the hazard risks were significantly increased in the intermediate albumin group, compared with the high albumin group, for death or OLT (3.6), liver-related death (11.2), HCC (4.6), decompensated cirrhosis (8.2), and gastroesophageal varices (6.2)." (PMID 37432160, 2023). "Long-term albumin replacement in patients with cirrhosis should be recognized more as medical therapy rather than as volume replacement." (PMID 37218881, 2023). "Furthermore, this study showed that ALB and GLS were independent predictors for GWE in patients with cirrhosis." (PMID 36970359, 2023). "However, in a recent randomized controlled trial, of outpatients with cirrhosis, prior HE, and current MHE, albumin infusions improved cognitive function and quality of life." (PMID 37396918, 2023). "Patients with cirrhosis had significantly lower platelet, alanine aminotransferase, albumin, and sodium levels compared to patients without cirrhosis." (PMID 35042464, 2022). "Arterial peritumoral hyperenhancement, non-smooth tumor margin, satellite nodules, cirrhosis, serosal invasion, and albumin showed a significant correlation with ER." (PMID 35756618, 2022). "Finally, age, sex, total bilirubin (TBIL), PT, albumin (ALB), PLT, hepatitis C virus antibody (anti-HCV), cirrhosis base on imaging, and CSPH were selected into the multivariable logistic regression." (PMID 35359352, 2022). "This indicates that chronic liver dysfunction had already progressed in cirrhosis, and that her liver was not able to synthesize albumin sufficiently." (PMID 38868660, 2022). "Serum albumin values were 17% lower in those with Child-Pugh B cirrhosis compared with controls, but these values were not significant." (PMID 35336003, 2022). "However, haemoglobin, platelet count, serum albumin and alpha-fetoprotein (AFP) levels were significantly higher in the HCC patients than the cirrhosis patients." (PMID 36099308, 2022). "In a preliminary study, DMN induced LC, by increasing GOT, GPT, total cholesterol, and ALP levels and by reducing final body weight, total protein, albumin, and liver weight; however, ISN protected the liver from cirrhosis and improved liver function compared to LC rats." (PMID 36559177, 2022). "Lower QoL of NAFLD has been verified to be related with elder age, female, low income and educational level, obesity, T2DM, fibrosis and cirrhosis, but not affected by liver enzymes or serum albumin." (PMID 36361098, 2022). "Our subgroup analyses indicate that patients with ACLF and cirrhosis without ACLF both had improved liver function with increased ALB levels and decreased MELD score." (PMID 35578365, 2022). "MSCs therapy was associated with increased ALB level at 4 weeks and 24 weeks in the ACLF subgroup, while only at 24 weeks in the cirrhosis without ACLF subgroup." (PMID 35578365, 2022). "Improvement of kidney function and an ascites reduction were observed when albumin was administered to patients with decompensated cirrhosis when diuretics failed to reduce ascites." (PMID 34281177, 2021). "Patients with cirrhosis and CDI had higher albumin and creatinine level than the patients with cirrhosis, but without CDI." (PMID 34204307, 2021).
Cirrhosis (continued). "The trial concluded that albumin infusion to increase serum albumin level to at least 3 g/dl had no benefit in patients hospitalized with decompensated cirrhosis." (PMID 34040918, 2021). "Univariate Cox regression analysis revealed that variables such as age, presence of cirrhosis, higher LS, lower platelet count, higher AST level, lower serum albumin, higher total bilirubin and higher total cholesterol were significantly associated with HCC development (all p < 0.05)." (PMID 34572795, 2021). "We also included questions regarding the use of albumin in non-established indications in the setting of cirrhosis, and about one third of physicians indicated to administer albumin in AVB and for hepatic encephalopathy." (PMID 33270161, 2021). "Another study showed no positive changes under the administration of albumin on patients with cirrhosis, even though there were three clinical trials to prove the benefit of albumin on patients with CLDs referred above." (PMID 34571946, 2021). "There exists evidence on the use of albumin in patients with cirrhosis and non-SBP infections or septic shock." (PMID 33270161, 2021). "As many as 47.7% of physicians would use albumin for treatment of hyponatremia in cirrhosis, but only 20.5% would administer albumin to cirrhotic patients with non-SBP infections/septic shock." (PMID 33270161, 2021). "In univariate analysis, cirrhosis, HE grades, infection, ascites, gastrointestinal bleeding, WBC, TB, INR, BUN, ALT, PLT, hemoglobin, Scr, NLR, Na, K, ALB, MELD, and MELD-Na showed a significant positive correlation with 90-day transplant-free mortality (p < 0.05) (data not shown)." (PMID 34532334, 2021). "Other scoring systems, such as albumin-bilirubin score and chronic liver failure-sequential organ failure (CLIF-SOFA) score, have been recently proposed for prognostic assessment of cirrhosis." (PMID 33933032, 2021). "In contrast, serum albumin (ALB) levels were significantly decreased in patients with PBC-AIH OS regardless of cirrhosis when compared to healthy control individuals." (PMID 32626734, 2020). "In contrast, serum albumin (ALB) levels were significantly lower in PBC patients regardless of cirrhosis than in healthy controls." (PMID 33178828, 2020). "Rates of virologic response were high regardless of cirrhosis status or liver disease severity, as indicated by low platelet counts or albumin levels." (PMID 32138687, 2020). "In our study, we evaluated the hypothesized predictors of response to albumin and terlipressin in type-1 HRS and cirrhosis patients treated with this protocol." (PMID 32076410, 2020). "According to the ROC curve for HCC occurrence based on the ALB level noted in 880 patients without cirrhosis (sensitivity, 58.82%; specificity, 74.11%; AUC, 0.7145), the best cutoff value for the ALB level before DAA treatment was 3.95 g/dl." (PMID 33284844, 2020). "ALB has the largest degree and BC in PPI network of advanced cirrhosis based on HCV." (PMID 33585012, 2020). "Improved liver albumin production with SVR was contributed by improved liver cell function rather than increased liver volume in patients with cirrhosis." (PMID 32310974, 2020). "These complications are thus not included among the accepted indications for albumin administration in decompensated cirrhosis [1••, 2•, 3•]." (PMID 32837825, 2020). "The albumin–bilirubin (ALBI) grade has been investigated to predict the prognosis of cirrhosis patients with or without hepatocellular carcinoma (HCC)." (PMID 31430975, 2019). "The main finding of the present study is that a mini-fluid challenge (150 ml of albumin 5%) is sufficient to assess fluid responsiveness in patients with Child A cirrhosis but not Child B or C cirrhosis." (PMID 30987597, 2019). "Cost-effectiveness analyses of the use of albumin to treat complications of cirrhosis are lacking, which are critical for appropriate healthcare decision making." (PMID 31278624, 2019).